CD38 (CD38 molecule)
Diseases named in the same sentence as CD38 in open-access papers (continued):
Sharing a sentence is not in itself a finding about the gene and the disease.
multiple myeloma (continued). "These promising results of our study indicate that CD38-specific hcAbs warrant further clinical development as therapeutics for multiple myeloma and other hematological malignancies." (PMID 32194826, 2020). "Panobinostat has been shown to increase CD38 expression on myeloma cells from patients with newly diagnosed multiple myeloma or refractory/relapsed disease." (PMID 32411240, 2020). "In this study, the expression of Tim3 was detected on myeloma cells (CD38+CD138+ cells) of bone marrow by flow cytometry (FCM) from 167 patients with MM and 51 healthy donors as controls and making correlation analysis with related clinical indexes." (PMID 33330064, 2020). "Rationale: CD38 is a target for the therapy of multiple myeloma (MM) with monoclonal antibodies such as daratumumab and isatuximab." (PMID 32194826, 2020). "Daratumumab targets CD38 on myeloma cells and a high level of CD38 expression facilitates complement-mediated cytotoxicity (CDC), antibody-dependent cellular cytotoxicity (ADCC) and antibody-dependent cellular phagocytosis (ADCP)." (PMID 32041300, 2020). "A Phase 2 dose-finding study evaluated isatuximab, an anti-CD38 monoclonal antibody, in relapsed/refractory multiple myeloma (RRMM; NCT01084252)." (PMID 32409691, 2020). "The efficiency of the TetOn system has been also tested for multiple myeloma (MM), using CD38 antigen as the target of Dox-regulated CAR T cells." (PMID 33013864, 2020). "The development of an anti-CD38 antibody as a therapeutic regimen alters the treatment landscape for multiple myeloma." (PMID 33003418, 2020). "As an antigen highly expressed on multiple myeloma cells, CD38 serves as a target for commercially available monoclonal antibodies that can be used in either the first-line setting or in the R/R setting with well-documented clinical efficacy." (PMID 32899464, 2020). "Subsequently, they exposed BM samples from MM patients containing CD38hiCD56hiCD319hi myeloma cells to the CD38-specific nanobody CAR-NK cells and showed significant lysis of primary myeloma cells compared to untransduced NK cells." (PMID 32707982, 2020). "In the myeloma setting, off-tumor toxicity profile of low affinity CD38 CAR T-cells has been evaluated." (PMID 32582204, 2020). "With daratumumab (an anti-CD38 mAb) approved for clinical application, CD38 has emerged as a high-impact therapeutic target in multiple myeloma." (PMID 32425977, 2020). "CD38 is an ideal target in the management of PC dyscrasia, including AL amyloidosis, and indeed anti-CD38 monoclonal antibodies (MoAbs) have promising therapeutic potential." (PMID 32531894, 2020). "The emerging therapeutic potential of anti-CD38 MoAbs in PC dyscrasias is addressed in this paper, and the initiallyavailable experiences with anti-CD38 MoAbs in AL amyloidosis are reviewed." (PMID 32531894, 2020). "DARA is the only anti-CD38 MoAb that has been formally examined over the last few years for the treatment of AL amyloidosis." (PMID 32531894, 2020). "Available data on the use of anti-CD38 MoAbs, especially in AL amyloidosis, are pivotal, but pave the way to studies aimed at characterizing novel therapeutic protocols." (PMID 32531894, 2020). "As previously emphasized, the relatively small percentage of clonally restricted plasma cells in AL amyloidosis expresses CD38, suggesting anti-CD38 MoAbs to be putatively effective in this disease." (PMID 32531894, 2020). "The experience with anti-CD38 compounds in MM is critical for the development of novel strategies of management of AL amyloidosis." (PMID 32531894, 2020). "Daratumumab, a human mAb, is a first-class anti-CD38 therapeutic antibody approved by FDA for the treatment of relapsed multiple myeloma in 2015 that represents unique cytotoxic activities." (PMID 31118070, 2019). "The first class of CD38-targeting antibody, daratumumab, is currently approved as a single agent and in combination with standards of care for the treatment of multiple myeloma." (PMID 31739402, 2019).
multiple myeloma (continued). "CD38 has been extensively studied for its role in hematological malignancies, including chronic lymphocytic leukemia and multiple myeloma." (PMID 31878283, 2019). "Nevertheless, it is well-established that CD38 overexpression is correlated to different hematological malignances including myelomas and leukemias." (PMID 31402913, 2019). "It has been reported that daratumumab induces the release of CD38 from myeloma cells by microvesicles." (PMID 31766279, 2019). "Lenalidomide was also shown to upregulate CD38 surface expression on myeloma cells, priming them for daratumumab-induced NK cell-mediated ADCC." (PMID 31569769, 2019). "CD38, a multifunctional protein that acts as both receptor and ectoenzyme, is overexpressed at all stages of myeloma." (PMID 31068926, 2019). "Daratumumab is the first in class CD38-targeting monoclonal antibody approved for the treatment of multiple myeloma (MM)." (PMID 32743508, 2019). "Previous studies have revealed that CD38 plays multiple functions in rheumatoid arthritis (RA), allergic airway disease, and multiple myeloma and is expressed in the membrane of immune cells." (PMID 31179321, 2019). "In contrast, normal plasma cells and multiple myeloma (MM) cells have high levels of CD38 expression, making CD38 an attractive target for therapeutic antibodies to treat MM." (PMID 31779273, 2019). "Its primary application is in multiple myeloma (MM) where CD38 is highly and uniformly expressed, but it is also being evaluated in lymphomas, including diffuse large B cell lymphoma, FL and mantle cell lymphoma, in AML and in ALL." (PMID 31636635, 2019). "The same is likely to also be true at diagnosis and early after ASCT, where several myeloma-promoting subsets expressed high levels of CD38." (PMID 31462637, 2019). "PEG-poly(α-benzyl carboxylate-ε-caprolactone) nanoparticles were decorated with anti-CD38 antibodies to target U266 myeloma cells." (PMID 30959799, 2019). "CD38 is also involved in multiple myeloma; antibodies against CD38, including daratumumab and MOR202, are promising therapeutics for multiple myeloma." (PMID 31179321, 2019). "Daratumumab is a fully humanized IgG1 mAb targeting CD38, a transmembrane glycoprotein that is overexpressed on myeloma cells." (PMID 31569769, 2019). "The most advanced of these developmental partnerships is with daratumumab (DARZALEX®; Janssen), the first approved monoclonal antibody for the treatment of multiple myeloma targeting CD38, an antigen highly expressed on multiple myeloma cells." (PMID 30744432, 2019). "The membrane glycoprotein cluster of differentiation 38 (CD38) is expressed at a high density by almost all myeloma cells, and at relatively low levels on normal hematopoietic cells." (PMID 31905752, 2019). "Daratumumab is a human mAb against CD38, currently tested on patients with multiple myeloma (MM) and other hematological malignancies." (PMID 31783629, 2019). "It is therefore likely that CD38+mPC interaction with CD31+BMSCs in the protective myeloma niche is hindered, leading to a reduction in pro-survival signals." (PMID 31068926, 2019). "Quantitative surface CD38 expression by multiple myeloma (MM) cells was the basic criterion used for therapeutic application of anti-CD38 monoclonal antibodies (mAbs)." (PMID 31783629, 2019). "In fact, the expression of DPP8 in CD38+ cells from myeloma patients was higher than that of healthy volunteers." (PMID 31792328, 2019). "Previous study demonstrates that transfer of mitochondria from astrocytes into neurons and from bone marrow stromal cells into multiple myeloma cells is mediated by CD38, a transmembrane glycoprotein catalyzing the production of cADPR." (PMID 31327963, 2019). "In this paper, we focus on the efficacy as well as toxicities of CD38 antibodies used both as a single agent and in combination as multiple myeloma treatment." (PMID 31842517, 2019).
multiple myeloma (continued). "Previous studies showed that CD38/cADPR signaling mediated mitochondrial transfer from astrocytes into neurons and from bone marrow stromal cells into multiple myeloma cells." (PMID 31327963, 2019). "In this sense, augmentation of CD38 expression in myeloma cells induced by agents such as all-trans retinoic acid (ATRA), or panobinostat, improved the efficacy of daratumumab both in vitro and in vivo." (PMID 31766279, 2019). "Treatment with Daratumumab (Dara), a monoclonal anti-CD38 antibody of IgG1 subtype, is effective in patients with multiple myeloma (MM)." (PMID 30759167, 2019). "It is also expressed at low levels on lymphoid and myeloid cells and in some tissues of non-hematopoietic origin; besides, many studies reported that myeloma cells express CD38 in the overwhelming majority of patients, although at varying surface densities." (PMID 31118070, 2019). "This target is of potential interest for AML, given that 75% of AML samples express CD38 and there are anti-CD38 mAbs approved for multiple myeloma with established safety profiles." (PMID 31434267, 2019). "HaNK cells were tested for cytotoxicity using the fully humanized anti-CD38 mAb Daratumumab (Darzalex®) against two multiple myeloma cell lines (RPMI-8226 and U266)." (PMID 30647406, 2019). "CD38 is highly and homogeneously expressed on normal PCs, as well as malignant PCs from multiple myeloma (MM) patients." (PMID 32743508, 2019). "Taken together, these studies indicate that therapeutic strategies that target CD38 activity would likely be effective in solid tumors in addition to hematologic malignancies like multiple myeloma." (PMID 31878283, 2019). "According to more recent work, panobinostat made a significant difference in inducing complete response in multiple myeloma by combining it with anti-CD38 monoclonal antibody (mAb) daratumumab, which was shown to be effective in multiple myeloma." (PMID 31067680, 2019). "CD38 is highly expressed on various malignant cells, including multiple myeloma (MM), and at relatively low levels in other tissues, making it a suitable target for therapeutic antibodies." (PMID 31779273, 2019). "This phase I dose-escalation/expansion study evaluated isatuximab (anti-CD38 monoclonal antibody) monotherapy in patients with relapsed/refractory multiple myeloma (RRMM)." (PMID 30926770, 2019). "We identified myeloma cells by their expression of CD38 and CD138 using fluorescence microscopy, and CD19 expression was evaluated by dSTORM with single-molecule resolution." (PMID 31316055, 2019). "Our results can help inform how anti-CD38 monoclonal antibodies can reshape the iTME if used at earlier stages of MM or AL amyloidosis." (PMID 31462637, 2019). "Now as we are close to the 10-year anniversary of dosing the first patient with daratumumab (March 26, 2008), it seems appropriate to review how far we have come in the development of this CD38 antibody for the treatment of multiple myeloma." (PMID 29915586, 2018). "Two CD38-specific antibodies (daratumumab, isatuximab) have recently been licensed for the treatment of multiple myeloma, since these tumor cells often upregulate cell surface expression of CD38 to very high levels." (PMID 29636685, 2018). "Recently an in vitro study showed that ricolinostat induced upregulation of CD38 expression on myeloma cells and had a synergistic effect in combination with daratumumab, an anti-CD38 antibody." (PMID 30096875, 2018). "In contrast, normal plasma cells and multiple myeloma (MM) cells have high levels of CD38 expression, which makes CD38 an interesting target for therapeutic antibodies targeting cell surface molecules in MM." (PMID 30294326, 2018). "Monoclonal antibodies against the cell surface antigen CD38, e.g., isatuximab, daratumumab, or Mor202, have entered the therapeutic armamentarium in multiple myeloma." (PMID 30079070, 2018).
multiple myeloma (continued). "The monoclonal antibody daratumumab, approved for treating myeloma, targets CD38, a protein on myeloma and also on CD34+ hematopoietic progenitor cells." (PMID 30356940, 2018). "We analyzed the capacity of these hcAbs to mediate complement-dependent cytotoxicity (CDC) to CD38-expressing human multiple myeloma and Burkitt lymphoma cell lines." (PMID 30524421, 2018). "Therapeutic targeting of CD38 is currently used for multiple myeloma and other hematologic malignancies and has also been proposed for SLE and other antibody-mediated autoimmune diseases." (PMID 30042766, 2018). "Since its expression is very high and uniform on myeloma cells, CD38 is a good target for novel therapeutic strategies." (PMID 30546360, 2018). "First, CD38-target expression has mainly been studied for either relapsed/refractory myeloma, small patient cohorts, or after gating using CD38 (among other markers) to identify the plasma cell population." (PMID 30079070, 2018). "Chromosomal alterations showed different patterns of association with CD38-expression (according to GEP, the largest cohort analyzed) in symptomatic myeloma." (PMID 30079070, 2018). "CD38 is highly expressed by multiple myeloma plasma cells and a small subpopulation of regulatory T cells (Tregs)." (PMID 30524421, 2018). "These biparatopic hcAbs elicited CDC toward CD38-expressing myeloma cells more effectively than daratumumab." (PMID 30524421, 2018). "The anti-CD38 daratumumab kills malignant PCs through traditional antibody-dependent cellular cytotoxic mechanisms that are potentially able to control myeloma disease." (PMID 30538704, 2018). "Here we discuss the advantages and disadvantages of CD38-specific hcAbs vs. conventional moAbs and provide an outlook for the potential use of CD38-specific hcAbs as novel therapeutics for multiple myeloma." (PMID 30459772, 2018). "The humanized monoclonal antibody, daratumumab, which targets CD38 has been approved for the treatment of relapsed multiple myeloma and is being explored in other lymphoproliferative disorders." (PMID 29966370, 2018). "The conventional CD38-specific moAbs daratumumab and isatuximab have proven therapeutic efficacy in multiple myeloma." (PMID 30459772, 2018). "With promising data, CD38 CAR T cells are currently in phase I trials against myeloma to test safety and dosing." (PMID 30031396, 2018). "A clinical trial is now being conducted with ATRA in combination with daratumumab to increase CD38 expression by myeloma cells and improve responses." (PMID 29915586, 2018). "This mini-review will summarize the present state of development of the CD38 antibody daratumumab for the treatment of multiple myeloma." (PMID 29915586, 2018). "High levels of CD38 have been described on a subpopulation of peripheral CD4+CD25+CD127dim regulatory T cells, which are sensitive to therapeutic intervention with the CD38-specific monoclonal antibody daratumumab in individuals with multiple myeloma." (PMID 29881878, 2018). "For our German-Speaking-Myeloma-Multicenter-Group (GMMG), this posed a surprising hurdle in defining the rationale of our CONCEPT trial (EudraCT 2016-000432-17), adding anti-CD38 treatment for symptomatic high-risk patients." (PMID 30079070, 2018). "At the same time, CD38-expression (according to GEP, the largest cohort analyzed) in symptomatic myeloma showed different patterns of association with adverse prognostic aberrations." (PMID 30079070, 2018). "While CD38 is expressed consistently on myeloma cells, it’s expression is limited on normal lymphoid and myeloid cells." (PMID 30031396, 2018). "The goal of this study was to assess the capacity of CD38-specific hcAbs to induce CDC to CD38-expressing multiple myeloma cells." (PMID 30524421, 2018). "This expression profile, together with the role of CD38 in adhesion and as ectoenzyme, resulted in the development of CD38 antibodies for the treatment of multiple myeloma (MM)." (PMID 30294326, 2018).
multiple myeloma (continued). "Since CD38 is overexpressed by multiple myeloma cells and other hematological tumors, it has attracted interest as a target for therapeutic antibodies." (PMID 30459772, 2018). "The relative hazard ratio of CD38-expression (symptomatic myeloma, including all cytogenetic entities) was comparable to those by adverse chromosomal aberrations and altered gene expression." (PMID 30079070, 2018). "Immediately after initiating therapy with daratumumab, the level of CD38 expression by myeloma cells is reduced to much lower levels." (PMID 29915586, 2018). "We determined that approximately 75% of CD34+ mobilized peripheral blood progenitor cells from myeloma patients en route to SCT co-expressed CD38, and then sought to determine the number of CD38 molecules per CD34+ cell." (PMID 30356940, 2018). "In view of the role of autologous SCT in patients with multiple myeloma, we investigated CD38 expression on mobilized CD34+ cells from myeloma patients and the binding and effect of daratumumab on mobilized CD34+ cells in vitro." (PMID 30356940, 2018). "CD38 is overexpressed by multiple myeloma cells and has emerged as a target for therapeutic antibodies." (PMID 30524421, 2018). "In bone marrow, the percentage of CD38-expressing myeloma cells ranged from 5% to 90% (mean: 38.9±22.82%) and that of CD138-expressing cells ranged from 5% to 90% (mean: 36.4±22.56%)." (PMID 29806594, 2018). "The bivalent tandem scFv of daratumumab mediated specific binding to CD38 expressing myeloma cells, while the engineered homotrimeric format of TRAIL induced apoptosis of these cells, presumably by binding to cognate death receptors." (PMID 30459772, 2018). "The reason for moving forward with testing of daratumumab for the treatment of multiple myeloma was the very high level of expression of CD38 by myeloma cells." (PMID 29915586, 2018). "It is obvious that DOX removal will also rapidly or eventually abrogate the anti-myeloma effect, depending on the CD38 expression levels on MM cells." (PMID 29847570, 2018). "Serum concentrations of Elo in these patients were >100 ug/ml at doses of 10 or 20 mg/kg with 80 or 95% median saturation of SLAMF7 on CD38+ myeloma cells in bone marrow, respectively." (PMID 30455698, 2018). "We find that CD38 is expressed on malignant plasma cells of all entities, including AL-amyloidosis, with two-log fold variation of expression within the respective entities." (PMID 30079070, 2018). "CD38 contributes to myeloma cell survival via adenosine production and subsequent calcium mobilization." (PMID 29900019, 2017). "We anticipate that anti-CD27 can be used to enhance the effects of other direct-targeting mAbs such as anti-CD38 in myeloma and anti-EGFR in solid tumors, and we are in the process of investigating this." (PMID 29198913, 2017). "Regarding CD38 and multiple myeloma, previous studies have revealed that this glycoprotein is strongly and homogeneously expressed in terminally differentiated normal and malignant plasma cells." (PMID 31548533, 2017). "mAbs against interleukin-6, B-cell activating factor CD138, Dickkopf 1 (DKK1), receptor activator of nuclear factor-κB ligand (RANKL), SLAMF7, and CD38 are currently in clinical development for the treatment of multiple myeloma." (PMID 28454113, 2017). "In preclinical studies, MOR202 killed CD38-expressing cell lines and primary myeloma cells from patients by ADCC and ADCP." (PMID 31548533, 2017). "Daratumumab (Darzalex) is a first-in-class inhibitor of CD38 and the first monoclonal antibody approved for treatment of myeloma." (PMID 29900019, 2017). "The results show specific discrimination of myeloma cells (CD45lo/CD56hi) with CD38-specific nanobodies." (PMID 29084989, 2017). "It is known that multiple myeloma (MM) cells express CD38 and that a recently developed human anti-CD38 monoclonal antibody Daratumumab mediates myeloma killing." (PMID 28915615, 2017).